FSHR (follicle stimulating hormone receptor)
Diseases named in the same sentence as FSHR in open-access papers (continued):
Sharing a sentence is not in itself a finding about the gene and the disease.
ovarian carcinoma (continued). "Due to the scarce amount of knowledge on AhR and its interaction with FSHR in ovarian cancer, an evaluation of AhR expression in different histological subtypes and of its correlation and impact on cancer biology and survival was the primary aim in the current study." (PMID 31212758, 2019). "FSHR expression in the ovarian cancer cells that we used has been reported previously." (PMID 29542355, 2018). "We have previously reported a targeted delivery system for paclitaxel and RNA interference (RNAi) drugs of growth-regulated oncogene α (gro-α) using FSHR-binding fragments as targeting moieties, which promoted the uptake of drugs by FSHR-expressing ovarian cancer cells." (PMID 29542355, 2018). "Approximately 70% of ovarian cancers express FSHR, as we previously reported." (PMID 29461120, 2018). "Therefore, this antibody was used to validate the FSHR expression in ovarian cancer, prostate cancer, and renal cancer tissues." (PMID 31548530, 2017). "The anti-FSHR immune receptor then triggered T-mediated cytotoxicity in ovarian cancer cells." (PMID 28439256, 2017). "Similarly, it was reported that overexpression of FSHR in OSE cells led to an increase in expression of proteins involved in ovarian cancer development such as EGFR, c-myc, and HER2/neu." (PMID 26635885, 2016). "If so, it may be also relevant for the outcome of tumours because, like in the ovary and ovarian cancers, FSHR may mediate the stimulatory effect of FSH on cell proliferation and angiogenesis and the inhibitory effect on apoptosis." (PMID 25685198, 2015). "Other conceivable molecules for targeting ovarian cancer cells include follicle-stimulating hormone receptor (FSHR), intercellular adhesion molecule 1 (ICAM-1), Müllerian inhibiting substance type II receptor (MISIIR), and human epidermal growth factor receptor 2 (HER2)." (PMID 24354786, 2013). "To find an effective targeted therapy strategy for ovarian cancer and a stable delivery system for siRNA, we developed an active targeted gene delivery system mediated by FSHR and showed its promising effects for down-regulating the target gene and suppressing ovarian cancer cells." (PMID 24252539, 2013). "Thus, targeting therapy mediated by FSHR has a high potential for ovarian cancer treatment." (PMID 38675151, 2024). "However, in combination with other factors like Luteinizing Hormone/Choriogonadotropin Receptor and Follicle Stimulating Hormone Receptor or Dkk2, it could serve as a positive prognostic factor for patients suffering from epithelial ovarian cancer." (PMID 33679613, 2021). "There is little information regarding the influence of FRBI on ARID1A, PTEN, and FSHR associated with ovarian cancers and no quantitative research has been reported about the correlation between ovarian carcinogenesis and levels of ARID1A and PTEN in humans and animals." (PMID 31241714, 2019). "Interestingly, murine T-cells directed against FSHR- positive ovarian cancer cells showed increased survival without causing toxicity." (PMID 30941099, 2019). "Thus, gro-α shRNA-loaded nanoparticles conjugated with FSH peptides could suppress tumor growth in FSHR-positive ovarian cancer in vivo." (PMID 29461120, 2018). "Therefore, FSHR is a rational target for receptor-mediated drug delivery in ovarian cancer." (PMID 29461120, 2018). "Reverse transcriptase-polymerase chain reaction (RT-PCR) analyses have shown, unequivocally, that FSHR is transcribed in extra gonadal tissues as well, particularly in the human female reproductive tract and the placenta, in benign prostatic hyperplasia, prostate cancer, and ovarian cancer." (PMID 31548530, 2017). "This study indicated that a FSHR-mediated delivery system could mediate the highly selective delivery of siRNA into ovarian cancer cells and that silencing gro-α expression could be a potential choice for ovarian cancer treatment." (PMID 24252539, 2013).
ovarian carcinoma (continued). "Other potential target molecules for targeting ovarian cancer cells might include follicle-stimulating hormone receptor (FSHR), intercellular adhesion molecule 1 (ICAM-1), Müllerian inhibiting substance type II receptor (MISIIR), or human epidermal growth factor receptor 2 (HER2)." (PMID 22509395, 2012). "To overcome this issue, we engineered CAR T cells redirected against ovarian cancer cells through the FSH hormone, the natural ligand of FSHR, expressed in ~60% of ovarian carcinomas of different histological subtypes." (PMID 38541651, 2024). "Several GPCRs are overexpressed in ovarian cancer including the lysophosphatidic acid receptor (LPAR), C-X-C chemokine receptor type 4 (CXCR4), follicle-stimulating hormone receptor (FSHR) and luteinizing hormone/choriogonadotropin receptor (LHCGR)." (PMID 40836974, 2024). "Clinically, few trials investigating CAR T-cell treatments for ovarian cancer are under way, with common targets including MSLN, FSHR, MUC16, and HER2." (PMID 36166071, 2023). "VSELs express FSHR and are easily mobilized and initiate ovarian cancer in presence of increased FSH thus supporting Gonadotropin theory of ovarian cancer." (PMID 34717703, 2021). "FSHR and LHCGR mRNA and protein expression were assessed in a range of human ovarian cancer cell lines by qRT-PCR and western blotting, respectively." (PMID 33374698, 2020). "Reflecting the role of β-arrestins as scaffold proteins linked to the GPCRs activity, correlations between the β-arrestin 2 and FSHR and LHCGR expression was identified ovarian cancer tissue." (PMID 33042017, 2020). "Using the publicly available CSIOVDB database, FSHR and LHCGR expression was increased in early-stage ovarian cancer (stage I) compared to stage II, III or IV cancers (p < 0.01)." (PMID 33374698, 2020). "We aimed to elucidate the prognostic impact of AhR, its correlation with the follicle-stimulating hormone receptor (FSHR), and their functional role in ovarian cancer." (PMID 31212758, 2019). "However, whether FSHR plays a role in ovarian cancer development is still uncertain." (PMID 31241714, 2019). "We previously developed FSHR-mediated nanoparticles and found that FSH peptides on the surface of nanoparticles have the potential to selectively deliver paclitaxel to ovarian cancer cells expressing FSHR." (PMID 29461120, 2018). "The expression patterns of follicle-stimulating hormone (FSH) receptor (FSHR) in normal and cancer tissues provide an opportunity for drug delivery with high selectivity in ovarian cancer." (PMID 29542355, 2018). "We previously developed FSHR-mediated nanoparticles and found that FSH peptides on the surface of nanoparticles improved the delivery of short interfering RNA (siRNA) into ovarian cancer cells." (PMID 29461120, 2018). "Thus, gro-α shRNA-loaded nanoparticles conjugated with FSH peptides could inhibit the proliferation, invasion, and migration abilities of FSHR-positive ovarian cancer cells, which may be due to the enhanced down-regulation of gro-α mediated by the nanoparticle complex." (PMID 29461120, 2018). "Here, we used FSHR as the target site and developed FSH peptide-modified nanoparticles to deliver shRNA into ovarian cancer cells." (PMID 29461120, 2018). "Follicle stimulating hormone receptor (FSHR) and luteinizing hormone receptor (LHCGR) were demonstrated to impact upon survival of patients suffering from epithelial ovarian cancer (EOC)." (PMID 23951246, 2013). "Since a common GPCR in ovarian cancer is the FSH receptor (FSHR), we investigated the prognostic significance of Her-2 in patients that had been stratified according to their FSHR status." (PMID 23339713, 2013). "However, preclinical studies suggest that blocking FSH-FSHR signaling with either FSH antagonists or FSHR antibodies is effective and safe to eliminate ovarian cancer in animal models." (PMID 39633710, 2024).
ovarian carcinoma (continued). "Expression of FSHR on VSELs and OSCs in the ovaries explains why commercially available ovarian cancer cell lines when treated with FSH do not show increase in cAMP." (PMID 34717703, 2021). "It has been shown that FSH activates ovarian cancer cell proliferation by acting on FSHR-3 rather than the canonical FSHR-1." (PMID 34717708, 2021). "Since follicle-stimulating hormone (FSH) receptor (FSHR) is overexpressed in ovarian cancer but not in nonovarian healthy tissues, we designed FSHR-mediated nanocarriers for HK2 shRNA delivery to increase tumor specificity and decrease toxicity." (PMID 33160373, 2020). "The ‘gonadotropin theory’ proposes that chronically elevated FSH and LH levels may lead to increased activation of FSHR and LHCGR, respectively, and subsequently stimulate ovarian cancer proliferation." (PMID 33374698, 2020). "However, few studies have explored the expression of FSH and LH receptors (FSHR and LHCGR) in ovarian cancer, and their functional roles in cancer progression remain inconclusive." (PMID 33374698, 2020). "FSHR is expressed in up to 50% of high grade serous ovarian cancer (HGSOC), however, limited studies have investigated the functional role of FSHR expression in ovarian cancer progression." (PMID 33374698, 2020). "This hormone was shown to be associated with an increased 5-years survival in LHCGR positive/FSHR negative ovarian cancer cases." (PMID 33042017, 2020). "Similarly, FSHR and LHCGR expression was increased in low-grade ovarian cancers (grade I), compared to high grade ovarian cancers (grade II or grade III, p < 0.01)." (PMID 33374698, 2020). "Previously, we had demonstrated that FP21 can bind to the FSHR of ovarian cancer cells specifically and did not affect cancer cell proliferation and metastasis." (PMID 29667478, 2018). "Follicular maturation is dependent on the development of follicle-stimulating hormone (FSH), and FSH receptor (FSHR) has been found in the ovarian surface epithelium (OSE) and in some ovarian cancer cell lines and tissues; above all, the distribution of FSHR is limited to the reproductive system." (PMID 29667478, 2018). "Their results showed that FSHR is a novel therapeutic target for ovarian cancer and the delivery of PTX via FSHP-NP could represent a novel therapeutic approach to ovarian cancer." (PMID 25610710, 2014). "Since a comparable amount of FSHR is also present in the FT, including the fimbriated end, certain high grade ovarian epithelial cancers with likely tubal origin do not negate the role of FSH in ovarian carcinogenesis." (PMID 23251297, 2013). "Some ovarian cancers, especially those poorly differentiated, lose FSH receptor (FSHR) expression." (PMID 22927847, 2012). "FSHR is also a potential target for non-hormonal contraception and in ovarian cancers." (PMID 37958944, 2023). "FORKO mice develop ovarian cancers despite complete elimination of FSHR and lack of ovulation." (PMID 34717703, 2021). "Our strategy was dual targeting of ovarian cancer via a MUC16 promoter trigger and FSHR mediation, which could enhance therapeutic specificity by avoiding the expression of passive-uptake shRNA drugs in non-cancer cells and which could reduce off-target effects." (PMID 29542355, 2018). "To specifically deliver genetic drugs including siRNA into ovarian cancer tissues, we recently developed a novel gene delivery system, polyethylene glycol (PEG)-polyethylenimine (PEI) complex modified with FSH β 33–53 peptide, to deliver siRNA carried by NPs into FSHR-positive cells." (PMID 24252539, 2013). "Because the exclusive expression of the FSHR has already been described by our group as a negative prognosticator in ovarian cancer cases, our finding about enhanced expression of both FSHR and THRα in the nucleus might lead to new treatment strategies for this type of cancer." (PMID 32533406, 2020).
ovarian carcinoma (continued). "Previously, we found that 17 of 24 primary human ovarian carcinoma specimens (70.83%) expressed FSHR, and there was no FSHR expression in the main organs of BALB/c mice bearing human ovarian carcinoma, such as the heart, liver, spleen, lung, and kidney." (PMID 29667478, 2018). "It is feasible that LH and FSH may promote ovarian cancer proliferation in the presence of FSHR and LHCGR however, tumor cells lacking LHCGR or FSHR no longer depend on gonadotropins for their growth and exhibit more aggressive behaviour." (PMID 33374698, 2020). "Ovarian cancer cell lines were used to study how FSH and LH regulate GPER and whether GPER activation differentially affects in vitro cell proliferation in presence/absence of activated FSHR/LHCGR." (PMID 23951246, 2013).
Infertility (59 papers, 2012 to 2026). "Sources revealed 235 different genes linked to ovulatory dysfunction and infertility including follicle-stimulating hormone receptor (FSHR), luteinizing hormone/choriogonadotropin receptor (LHCGR), and bone morphogenic protein 15 (BMP15)." (PMID 40535332, 2025). "The FSHR gene and SNPs associated with it have been found to be predictive of fertility, delayed puberty and infertility in humans, and cattle." (PMID 38939530, 2024). "Research examined the distribution of AMHRII -482A>G and FSHR Ser680Asn polymorphisms in 126 infertile women versus 100 fertile women." (PMID 39735088, 2024). "Understanding the relationship between the observed infertility phenotypes, receptor-specific activation of the MAPKs and Akt, and the elevated levels of FSHR and LHR in the testes in Atp10A deficient mice requires further study." (PMID 38415274, 2024). "Numerous studies have shown that FSHR mutations are indicators of fertility and infertility during female reproduction." (PMID 37235159, 2023). "FSH acts through FSHR, which is present in the plasma membrane of granulosa cells.For some years, the occurrence of polymorphisms in FSHR has been studied andreported in infertile women." (PMID 36995260, 2023). "In other words, among patients with poor response, women with infertility with adequate ovarian reserve exhibited a higher frequency of FSHR (rs6166) A allele than women with infertility with low ovarian reserve." (PMID 36769444, 2023). "Partial or total inactivation of FSHR, caused by the abnormal structure of the receptor, can be found in various disorders, such as infertility, amenorrhea and premature ovarian failure." (PMID 36768772, 2023). "A higher frequency of FSHR (rs6166) A allele was observed in the women with infertility with adequate ovarian reserve (POSEIDON group 1 and 2)." (PMID 36769444, 2023). "We found 19 specific high-confidence interacting proteins for WT FSHR and 14 for A189V FSHR, several of which have been linked to infertility." (PMID 35471239, 2022). "The study of our patient demonstrates that total FSHR inactivation in humans causes infertility with an early block of follicular maturation remarkably associated with abundant small follicles, as in prepubertal ovaries." (PMID 34884539, 2021). "For example, a splice site variant, which results in exon two deletions in the FSHR gene and affects the extracellular domain of FSHR protein and the reduced response of the receptor, was found in women who received infertility treatment." (PMID 33561079, 2021). "Generally, the mutations and polymorphisms in FSHR genes bring about diverse activity of this receptor for infertility medicines and treatment procedures as well as IVF and ICSI (intra-cytoplasmic sperm injection) in females." (PMID 33561079, 2021). "FSHR inactivating mutations cause primary or secondary amenorrhea, infertility, and premature ovarian failure (POF), whereas activating mutations can predispose to ovarian hyperstimulation syndrome (OHSS)." (PMID 34717708, 2021). "In some cases, inactivating homozygous FSHR mutations in humans were associated with infertile male phenotypes, although these mutations are very rare, and the issue is a matter of debate and merits additional investigations." (PMID 32260182, 2020). "The first published European study assessed the distribution of the two most common FSHR polymorphisms in 148 normogonadotropic anovulatory infertile women and in 30 normo-ovulatory controls." (PMID 30809190, 2019). "Recent genetic studies have revealed that the pathogenesis of subfertility or infertility can be due to mutations in the follicle-stimulating hormone receptor (FSHR) gene." (PMID 29954364, 2018). "We additionally assessed the ovarian response to COS as well as the time and amount of gonadotrophins required to reach a mean follicle diameter of 18 mm in normal oocyte donors and infertile patients from the IVF group bearing different N680S FSHR variants." (PMID 30340493, 2018).